ITGB4 (integrin subunit beta 4)
Diseases named in the same sentence as ITGB4 in open-access papers (continued):
Sharing a sentence is not in itself a finding about the gene and the disease.
tumor (continued). "We also found a visibly stronger expression of L1-CAM, CD44, and ITGB4 in the scid mice primary tumours and lung metastases injected with Fra-2 overexpressing cells by immunohistochemical staining." (PMID 34693476, 2022). "TAp73, a tumor suppressor inducing apoptosis and cell cycle arrest, has been shown to bind the ITGB4 promoter region to stimulate ITGB4 transcription." (PMID 36612146, 2022). "Budding was observed in primary HNSCC with a homogeneous and an edge localization of ITGB4-positive tumor cells." (PMID 36076232, 2022). "The EPHA2, ITGB4, and COL4A5 genes have been associated with tumor progression by exhibiting cell invasion and metastasis." (PMID 34299042, 2021). "These two therapies reduced ITGB4-expressing CSCs and inhibited local tumor growth and lung metastasis through ITGB4 specific cellular and humoral immune responses." (PMID 34504657, 2021). "In tumor tissues, phosphorylation of the cytoplasmic tail of ITGB4 led to its release from the semi-desmosome and its interaction with the growth factor receptor." (PMID 34402716, 2021). "In our second approach, we generated an anti-CD3/anti-ITGB4 bispecific antibody and bound it to activated and expanded tumor draining lymph node (TDLN) T cells." (PMID 34504657, 2021). "With ITGB4 expression found on several tumor types, immunological targeting of CSCs through ITGB4 protein-pulsed DC vaccination provides a more accessible route to clinical relevance." (PMID 34504657, 2021). "We have shown in the 4T1 and SCC7 mouse models that both unsorted tumor cells and ALDHhigh CSCs express ITGB4, and immunological targeting of ITGB4 combined with anti-PD-L1 immunotherapy elicits significant anti-tumor immunity." (PMID 34504657, 2021). "The 4T1 and SCC7 murine tumor cells expressed ITGB4 and PD-L1 on bulk tumor cells and ALDHhigh CSCs, making both proteins viable immunological targets." (PMID 34504657, 2021). "In particular, ITGB4 expression was significantly increased in SKCM tissues compared with non-tumor tissues." (PMID 34660316, 2021). "But in cancer cells, ITGB4 was redistributed from HDs to the anterior edges of cells enriched in the lamellar and filamentous feet, enhancing tumor migration and invasion." (PMID 34402716, 2021). "Then, in UALCAN database, we found JUP and ITGB4 were higher expressed in tumor while ST3GAL5 and ST8SIA1 were lower expressed in tumor." (PMID 34402716, 2021). "Of note, after an observable reduction in tumor growth and metastasis following ITGB4-DC vaccination plus anti-PD-L1 immunotherapy, we found increased serum levels of IFN-γ and IL-6 compared to controls in both the 4T1 and SCC7 models." (PMID 34504657, 2021). "Assessing the efficacy of our ITGB4-DC vaccine in these two tumor models, we found that vaccination combined with anti-PD-L1 immunotherapy significantly reduced tumor growth and inhibited spontaneous pulmonary metastasis better than each monotherapy." (PMID 34504657, 2021). "Together, these results emphasize ITGB4 as a practical CSC immunological target with possible therapeutic benefits across tumor types with high ITGB4 expression." (PMID 34504657, 2021). "Together, these findings support the use of ITGB4-targeted treatment, combined with anti-PD-L1 immunotherapy, as a method to specifically target ITGB4-expressing tumor cells and CSCs." (PMID 34504657, 2021). "Bispecific antibodies can elicit a diverse effector T cell population through CD3 binding, and guide these cytotoxic effectors towards a specific tumor antigen, e.g. ITGB4." (PMID 34504657, 2021). "EGFR is involved in the acquisition of self-sufficient growth-stimulatory signaling, while ITGB4 promotes the tumor ability for invasion and metastasis." (PMID 32886718, 2020). "As expected, the levels of protein expression of the three high-risk genes (ITGB4, CDKN2A, and ERO1A) were demonstrably higher in tumour tissues with more intense antibody staining and a greater proportion of stained cells." (PMID 32238163, 2020).
tumor (continued). "The associations of ITGB4 expression with clinicopathological parameters including gender, age, T stage, N stage, M stage, TNM stage, tumor location, and MSI status were investigated in all available datasets and in integrated analyses." (PMID 31602273, 2019). "In tumour tissues, the phosphorylation of the cytoplasmic tail of ITGB4 leads to its release from hemidesmosomes and its interaction with growth factor receptors, which promotes the invasion and metastasis of tumour cells." (PMID 30658712, 2019). "They contained typical horn pearls, rarely displayed surface ulcerations and the tumor cells expressed keratin 5 (Krt5) and β4-integrin (Itgb4) in basal layers, and keratin 10 (Krt10) in upper layers when present." (PMID 31803622, 2019). "Compared with in normal tissues, the level of miR-133b was decreased, while EGFR and ITGB4 mRNA levels were enhanced in tumor tissues." (PMID 30479571, 2018). "ITGB4 has been suggested to be up-regulated in multiple tumors and contribute to tumor progression by promoting proliferation, invasion and EMT process." (PMID 30479571, 2018). "The expression of ITGB4 was assessed in paired tumor and adjacent non-tumor samples from 82 patients with HCC by immunohistochemical staining and real-time qPCR." (PMID 28084395, 2017). "Our results were confirmed in vivo in a xenograft tumor model induced by injection of ITGB4-overexpressing cells into nude mice, which showed that ITGB4 promoted tumor growth and metastasis to the lungs." (PMID 28084395, 2017). "In tumor tissues, the phosphorylation of the cytoplasmic tail of ITGB4 leads to its release from hemidesmosomes and its interaction with growth factor receptors, which promotes the invasion and metastasis of tumor cells." (PMID 28084395, 2017). "In a xenograft tumor model induced by injection of ITGB4-overexpressing cells into nude mice, ITGB4 promoted tumor growth and metastasis to the lungs." (PMID 28084395, 2017). "The effect of ITGB4 was assessed in a xenograft tumor model induced by injection of ITGB4-overexpressing Bel-7402 cells into nude mice." (PMID 28084395, 2017). "ITGB4 was initially identified as a tumor-related antigen upregulated in multiple cancer cells, so investigating compounds selective for ITGB4 for cancer therapy is of interest." (PMID 26918348, 2016). "Tyr1494 in ITGB4 functions as a master regulator controlling multiple signal transduction pathways closely related to tumor progression." (PMID 26918348, 2016). "ITGB4 Y1494 controls anchorage-independent tumor growth by activating ERK1/2 signaling and invasion by activating PI3K and Src." (PMID 26918348, 2016). "Integrin β4 (ITGB4) is the structural component of hemidesmosomes (HDs) that maintains epithelial architecture and also acts as a signaling adaptor driving tumor cell proliferation and movement." (PMID 26918348, 2016). "In summary, we found that a small molecule, SEC, selectively promoted apoptosis in tumor cells with high expression of ITGB4." (PMID 26918348, 2016). "ITGB4 is abundant in the 4 kinds of tumor cells, and SEC dose-dependently decreased the cell viability." (PMID 26918348, 2016). "This behavior of promoting tumor progression explains the upregulation of ITGB4 in multiple cancer cells and suggests that ITGB4 redistribution affords cells with advantages for proliferation and invasion." (PMID 26918348, 2016). "In carcinoma cells, ITGB4 redistributes from HDs to the leading edges of cells enriched at lamellipodia and filopodia and promotes tumor migration and invasion." (PMID 26918348, 2016). "Most studies have focused on the involvement of ITGB4 in tumor proliferation, invasion and metastasis." (PMID 26918348, 2016). "Here, we highlight the physiological significance of ITGB4 nuclear translocation in promoting tumor cell apoptosis." (PMID 26918348, 2016). "Both false positive cases had a tumor size of over 35 mm, suggesting a higher diagnostic reliability for [high-ITGA3/CD9 and high-ITGB4/JUP] status in early OSCC." (PMID 24006899, 2013).
tumor (continued). "Primary site recurrence (PSR) was significantly associated with high-ITGA3/CD9, tumor size, T3-4 and positive margin, while distant metastasis was associated with high-ITGA3/CD9, a high ITGB4/JUP ratio (high-ITGB4/JUP), and YK4." (PMID 24006899, 2013). "Integrin beta 4 (ITGB4) is a laminin receptor that is upregulated in tumor cells and angiogenic endothelial cells." (PMID 21072196, 2010). "Conversely, genes that are widely overexpressed in tumours like Mucin 1 (Muc1), the protease cathepsin B (Ctsb) and integrin, beta 4 (Itgb4) remained upregulated upon treatment with the dual kinase inhibitor." (PMID 21152443, 2010). "Therefore, the anti-tumor effect of ZGS II depends on the reduced activation of the ITGB4/FAK signaling pathway." (PMID 42290049, 2026). "Additionally, tumor adhesion and metastasis-promoting molecules, including ITGB4 and ITGB8, whereas ITGA1 and ITGA2 were downregulated in ST6GAL1-knockdown cells." (PMID 39937175, 2025). "Taken together, these findings suggest that tumor basal stem‐like cells in PSCC may activate the ITGA6/ITGB4 signaling axis through both autocrine and paracrine pathways involving Laminin‐332, thereby promoting tumor invasion." (PMID 40470730, 2025). "We found that among 17 genes tested, ITGB4, a well-known gene involving tumor migration and invasion, was the only gene whose downregulation by MLN4924 was significantly rescued by both approaches, while a minimal rescue or rescue only by one approach was observed in the other 16 genes." (PMID 40784455, 2025). "Together with the observation that ITGB4 was the only gene of the 5-gene signature also identified as fDEG and component of the invGRN, the current data suggest a central role for ITGB4 in the complex re-programming of tumor cells towards local invasion and in response to EGFR-based treatment." (PMID 40121428, 2025). "In the present study, low signal levels of ITGA2–UEA and ITGB4–MAA assays from serum were significantly associated with both tumor recurrence and negative radiotherapy response." (PMID 40287842, 2025). "However, interestingly, low signal levels in two lectin assays from serum, namely, ITGA2–UEA and ITGB4–MAA, were significantly associated with both tumor recurrence and poor radiotherapy response in ROC analysis as well." (PMID 40287842, 2025). "ITGB4 has been identified as a key player in promoting the metastasis of various tumor cells." (PMID 40784455, 2025). "Notably, the Tum_1 subtype showed elevated expression of LAMC2, which facilitated tumor invasiveness through its interaction with ITGA6/ITGB4." (PMID 40470730, 2025). "However, in tumors, ITGB4 is located at the front of the cell, which is rich in lamellae and filopodia, thereby enhancing tumor migration and invasion." (PMID 39132499, 2024). "Our immune infiltration data show that ITGB4 expression negatively correlates with tumor purity and positively correlates with immune and stromal scores, indicating that ITGB4 may be a potential therapeutic target in the TME." (PMID 38172503, 2024). "ITGB4 exhibits high expression levels in numerous tumors, making it a potential tumor marker." (PMID 39169946, 2024). "ITGB4 works with different molecules to regulate tumor migration and invasion." (PMID 39169946, 2024). "The influence of ITGB4 on tumor migration and invasion extends beyond canonical signaling pathways." (PMID 39169946, 2024). "Furthermore, methylation and genetic alterations within the ITGB4 gene hold significant promise for tumor diagnosis and treatment development." (PMID 39169946, 2024). "Our data suggest on the one hand that the unfavorable prognostic effect of high ITGB4 levels might be due to reduced counts of anti-tumor MDSCs." (PMID 36932441, 2023). "However, after depletion of ITGB4, the main phenotype was already apparent at the primary tumor level in terms of moderately delayed tumor growth." (PMID 36932441, 2023).
tumor (continued). "Furthermore, several studies have reported that the expression of ITGB4 throughout the tumor tissue correlates with a poor prognosis." (PMID 37371594, 2023). "Additionally, ITGB4+PD-L1+ tumor cells were positively correlated with CD8+PD-1+ T cells (positivity p = 0.02, positive number p = 0.03)." (PMID 37371594, 2023). "Intriguingly, the ITGB4 status of the TCs and the E-/P-selectin status of the tumor stroma also affected the local immune environment in these immunocompetent hosts: under both conditions per se, the number of CD3+ cells specifically increased at the tumor margin, but not in the tumor center." (PMID 36932441, 2023). "Previous findings demonstrated that ITGB4 promotes tumorigenesis and tumor progression." (PMID 36385523, 2023). "Conversely, a pathological expression means that ITGB4 was found throughout the tumor tissues." (PMID 37371594, 2023). "Moreover, with a synergic analysis of ITGB4 and PD-L1 expression levels, we found that high levels of ITGB4 and PD-L1 in the tumor tissues of OSCC patients indicate a remarkably favorable prognosis." (PMID 37371594, 2023). "In the tumor area, the results showed a statistically significant association between ITGB4 and PD-L1 in terms of positive numbers (p = 0.005), but not in terms of positivity (p = 0.23)." (PMID 37371594, 2023). "The ITGB4 KD per se again had a detectable, but less striking effect on tumor growth." (PMID 36932441, 2023). "Besides these effects on the local tumor immune environment, the ITGB4 KD also changed the systemic immune environment within only 10 days upon TC inoculation." (PMID 36932441, 2023). "Therefore, it was reasonable to assume that the delayed tumor growth in the ITGB4 KD group was at least in part due to enhanced apoptosis." (PMID 36932441, 2023). "Our work also highlighted the role of ITGB4 in defining tumor heterogeneity." (PMID 36675528, 2023). "We speculate that the augmented infiltrated exhausted T cells in high ITGB4-expressing tumor cells induced a sequencing elevated level of PD-L1." (PMID 37371594, 2023). "Overall, these results demonstrate that ITGB4+PD-L1+ tumor cells may induce the accumulation of CD8+ T cells and consequently result in the exhaustion of CD8+ T cells." (PMID 37371594, 2023). "Furthermore, we evaluated the possible link between the ECMGs and the tumor stage of PAAD, and 8 ECMGs (i.e. FN1, LAMA3, ITGB6, ITGB4, ITGA2, LAMC2, COL11A1, LAMB3) were detected to be significantly associated with tumor stage." (PMID 36311789, 2022). "Moreover, the downregulation of ITGB4 leading to HD disassembly is strongly correlated with PCa progression, metastasis, tumor stage, Gleason score, prostate-specific antigen (PSA) level and worse patient survival." (PMID 36612146, 2022). "Tumor ITGB4 appears to play a role in the regulation of stem cell properties and immunosuppression." (PMID 35805064, 2022). "Meanwhile, it requires more effort to determine whether ITGB4 has any impact on other biological behaviors of this neoplasm." (PMID 35305660, 2022). "Finally, we used TIMER database determine the correlations between GALNT3, CYCS, EIF5A, and ITGB4 and six types of tumor-infiltrating immune cells." (PMID 35651789, 2022). "Following the steps of the metastatic cascade, integrins like ITGB4, which was highly expressed in Fra-2 overexpressing scid tumours, are also O-glycosylated and are suspected to influence the attachment of tumour cells to the ECM as well as cell-to-cell interactions." (PMID 34693476, 2022). "Additionally, ITGB4 expression was analyzed in scRNA-seq datasets of different cancer entities using TISCH (Tumor Immune Single-Cell Hub)." (PMID 36076232, 2022). "Laminin 5 co-localized with ITGB4 at the tumor-stroma interface." (PMID 36076232, 2022). "Additionally, EGFR, Mucin-1 (MUC1), and integrin beta-4 (ITGB4), which promote tumor growth and metastasis, are poor prognostic factors for this tumor." (PMID 36407096, 2022).
tumor (continued). "Notably, several genes related to matrix composition and immune cell recruitment were upregulated in squamous cells (Anxa1, Ecm1, Il1rn, Itgb4), as well as genes that are reported to be tumor suppressors (Serpin5b, Phlda3)." (PMID 35600339, 2022). "Similarly, we observed diminished tumor growth and metastasis in established tumors after adoptive transfer of ITGB4-BiAb armed TDLN cells plus anti-PD-L1 administration." (PMID 34504657, 2021). "Therefore, the phenotype of ITGB4 in different tumor cells appears to be more complicated than expected, and further research is needed." (PMID 34414684, 2021). "Additionally, 4T1-ITGB4KO tumors showed improved growth responses compared to both untreated and treated WT-4T1 tumors, implying that ITGB4 signaling participates in tumor development within the 4T1 model." (PMID 34504657, 2021). "In tumours, ITGB4 was first discovered as a tumour-specific antigen." (PMID 30658712, 2019). "The size and weight of xenograft tumours were significantly reduced by the ITGB4 knockdown." (PMID 30658712, 2019). "From these results, we found that miR-133b level was negatively correlated with EGFR and ITGB4 levels in tumor tissues, which may participate in the metastasis of ESCC." (PMID 30479571, 2018). "ITGB4 promoted tumor growth in a xenograft tumor model in vivo." (PMID 28084395, 2017). "We discovered a chiral small molecule, SEC, that could specifically induce apoptosis of tumor cells with high ITGB4 content by promoting ITGB4 nuclear translocation." (PMID 26918348, 2016). "The loss of ITGB4 expression reduced the Shh-stimulated cellular invasion of SKOV3 cells by ∼60% compared with untreated or non-targeting (miR-control) miRNAi–transfected cells, suggesting that ITGB4 is important for tumor cell invasion." (PMID 24533083, 2014). "Additionally, laminin encoded by LAMA4, LAMB1, and LAMB2 mediate adhesion through Integrin binding—specifically the Integrin α6β4, composed of integrin α6 (ITGA6) and Integrin β4 (ITGB4)—is suggested to be essential for tumor development and progression, promoting pro-cancer signaling pathways." (PMID 40333631, 2025). "Similarly, several genes encoding proteins involved in tumor shedding, adhesion and migration, such as collagens (COL4A5, COL4A6), integrins (ITGB4) and laminins (LAMA3), were overexpressed and positively associated with pathogenic bacteria in OSCC tumor microenvironment." (PMID 38589501, 2024). "Based on the function of ITGB4 in cancer stem cells, immunologic strategies targeting ITGB4 combined with dendritic cells or anti-ITGB4 antibodies armed with tumor-draining lymph node T cells showed benefits in suppressing tumor growth and metastasis in xenograft mouse model." (PMID 38814534, 2024). "Therefore, CTCs with the ITGA6 and ITGB4 expression have a set of potencies that could lead to tumor cells spread across the body." (PMID 38250718, 2024). "Notably, the function of ITGB4 varies across different tumor types." (PMID 39169946, 2024). "Interestingly, ITGB4 expression was enhanced at the tumor margin of PC-3 xenografts (arrowheads)." (PMID 36932441, 2023). "Hence, we speculate that the recruitment and infiltration of CD8+ cells may be due to the interaction of immune cells with ITGB4+ tumor cells at the tumor– stroma margin." (PMID 37371594, 2023). "We observed a very robust synergism between ITGB4 and E-/P-selectin for the regulation of tumor growth, accompanied by an increased recruitment of CD11b+ Gr-1Hi cells with low granularity (i.e., myeloid-derived suppressor cells, MDSCs) specifically into ITGB4-depleted tumors." (PMID 36932441, 2023). "Interestingly, the enhanced release of CXCL2 from ITGB4 KD PC-3 cells could be reversed by treating the tumor cells with the STAT inhibitor fludarabine." (PMID 36932441, 2023).